MMP20 (matrix metallopeptidase 20)
Diseases named in the same sentence as MMP20 in open-access papers (continued):
Sharing a sentence is not in itself a finding about the gene and the disease.
lung adenocarcinoma (1 paper, 2021). A carcinoma that arises from the lung and is characterized by the presence of malignant glandular epithelial cells. "To prove this, we aimed to determine the downstream effect on the A549 lung adenocarcinoma cell proliferation following knock-down of MMP20 gene expression by using CRISPR-Cas9 method." (PMID 33914777, 2021). "In this study, two different single guide RNA (sgRNAs) that specifically targeted on MMP20 sites were transfected into human lung adenocarcinoma A549 cells by using CRISPR-Cas method." (PMID 33914777, 2021). "The current study demonstrated that knock-down of MMP20 gene in A549 lung adenocarcinoma cells was accompanied by a reduction of cell survivability, as shown in the AO/PI stains and migratory activities." (PMID 33914777, 2021). "More studies should be carried out in the future to evaluate the safety and efficiency of CRISPR-Cas technologies for knocking down MMP20 gene in lung adenocarcinoma animal models." (PMID 33914777, 2021). "Specific targeting on MMP20 gene could potentially provide an efficient form of treatment to halt lung adenocarcinoma progression." (PMID 33914777, 2021). "The knock-down of MMP20 gene in human A549 lung adenocarcinoma could trigger cell death and decrease cell migration in the in vitro assay." (PMID 33914777, 2021). "The current study aimed to identify the functional properties of MMP20 on cell proliferation and motility in a lung adenocarcinoma in vitro cell model, and relate the interaction of MMP20 with other molecular signalling pathways in the lung cells after gaining tumoral properties." (PMID 33914777, 2021). "Also, future efforts should explore targeting MMP20 gene as a form of treatment for lung adenocarcinoma." (PMID 33914777, 2021). "Thus, it is interesting to determine the interaction of MMP20 with other signalling molecules in lung adenocarcinoma and the cellular behavioural changes after MMP20 knock-down." (PMID 33914777, 2021). "The role of MMP20 is not well studied in lung organogenesis, however, it was previously shown to be present at high level in lung adenocarcinoma." (PMID 33914777, 2021).
lymph node metastasis (1 paper, 2021). "The team observed over-expression of MMP20 in LSCC when compared to the adjacent normal tissues, which implies that MMP20 could be used as a prognostic marker for lymph node metastasis." (PMID 33681393, 2021).
migraine (1 paper, 2022). "Also, our combined gene-based analysis identified three migraine-associated MMPs, including MMP7, MMP20 and MMP27." (PMID 35546551, 2022).
Sepsis (1 paper, 2014). Sepsis is defined as life-threatening organ dysfunction caused by a dysregulated host response to infection. "The association of the MMP-1 (-1607 1G/2G) SNP and sepsis might be due to linkage disequilibrium with the MMP-13 SNP because the MMP-13 and MMP-1 genes are both located in the same cluster of the chromosome 11q22-23 along with the MMP-3, MMP-7, MMP-8, MMP-10, MMP-12, and MMP-20 genes." (PMID 24833564, 2014).
thyroid cancer (1 paper, 2019). "Furthermore, MMP20 levels increased with advanced stages of colon and thyroid cancers." (PMID 30932369, 2019).
cancer (16 papers, 2016 to 2024). A tumor composed of atypical neoplastic, often pleomorphic cells that invade other tissues. "MMP-20 catalysed the degradation of the enamel organic matrix following radiotherapy in cancer patients, which could lead to enamel delamination associated with HNRT." (PMID 31880287, 2020). "A key protein in human tooth embryonic development, namely matrix-metalloproteinase 20 (MMP20), has been identified in various tumor entities, and is thus suggested to be useful as novel biomarker for cancer diagnosis." (PMID 35330493, 2022). "A very recent study by Aseervatham and Ogbureke investigated the effect of MMP20-DSPP silencing on several cancer related phenotypes such as epithelial-mesenchymal transition, cell adhesion, angiogenesis and metastasis." (PMID 33681393, 2021). "Dentin sialoprotein phosphoprotein (DSPP), a member of the Small Integrin Binding Ligand N-linked Glycoprotein (SIBLING) and its cognate Matrix Metalloproteinase partner (MMP20), is upregulated in several human cancers." (PMID 32630820, 2020). "EGFR, ERBB3, MMP20, MMP27, MCL1, BCL2A1 and BAK1 appear to be important genes for cancer progression due to their frequent association with recurrent cancer-related genes in women." (PMID 31205821, 2019). "On the other hand, MMP20‐DSPP staining intensity was higher in neoplastic counterparts (carcinomas and adenocarcinoma) of the prostate, colon, and thryroid." (PMID 30932369, 2019). "These carcinoma results support our data demonstrating increased cell invasion with increased MMP20 expression." (PMID 27403713, 2016). "Taken together, it is rationale to speculate that MMP20 may have modulatory properties on cell cycle that leads to uncontrolled cell proliferation in cancer development, in addition to its role in cell metastasis." (PMID 33914777, 2021). "Similarly, immunofluorescence indicated MMP20‐DSPP co‐expression in cancer cell lines and in normal but transformed cell lines from the colon (Colo320, Caco2), prostate (LNCap, PEpic), and cervix (DoTC2, SiHa, ECT1)." (PMID 30932369, 2019). "Further studies found MMP-19 and MMP-20 high expressions could cause drug resistance and cancer invasion, providing potential molecular mechanisms for the poor prognosis caused by high MMP-19 and MMP-20 expressions." (PMID 31406154, 2019). "Some MMPs had very high numbers of transcripts present (gene cluster A), while six MMPs in gene cluster C (MMP27, MMP21, MMP20, MMP26, MMP23A, and MMP8) featured scant numbers of transcript copies across any cancer tissue." (PMID 31200666, 2019). "Previous studies have also shown that MMPs are involved in cancer metastasis and invasion, so we also investigated the influence of MMP-19 and MMP-20 on cell invasion abilities using the Boyden chamber method." (PMID 31406154, 2019). "Our previous reports also have established that a number of matrix metalloproteinases (MMPs), known to be upregulated in cancers, including OSCC, bind and interact with specific MMPs in biochemical and biologic systems: MMP2 with BSP; MMP3 with OPN; MMP9 with DMP1; and MMP20 with DSPP." (PMID 30002682, 2018). "On the bases of these numerous reports linking CSC marker expression with various aspects of cancer biology, it is therefore reasonable to speculate that the changes observed with OCSC following DSPP/MMP20 silencing may be translatable into several anticancer effects." (PMID 30002682, 2018). "MMP-19 and MMP-20 knockdown did not increase Cov362 resistance to Paclitaxel (both p > 0.05), which might due to the fact that different molecular mechanisms are involved in the anti-cancer effects of these drugs." (PMID 31406154, 2019).
tumor (9 papers, 2016 to 2024). "The expression of MMP20 along with DSPP was assessed in several tumor types of breast, colon, prostate, thyroid and cervical region." (PMID 33681393, 2021). "The results demonstrated that the level of expression of MMP20 increased with increasing grade of tumor." (PMID 33681393, 2021). "The study also documents that the level of MMP20 increased as the tumor progressed to subsequent stages, thus suggesting that this combination could be a lethal duo in the process of tumorigenesis." (PMID 33681393, 2021). "Thus these results indicate that the tumorigenic effect of MMP20/DSPP is mediated by the up-regulation of genes potentially involved in steps leading to tumor development, progression and invasion." (PMID 33681393, 2021). "HCC cells with increased serine protease inhibitor Kazal-type- (SPINK-) 6 expression associate a significant downregulation of MMP-20, as well as MMP-9, suggesting that MMP-20 may also play a role in ECM degradation and tumor cell invasion and migration." (PMID 31886121, 2019). "We employed immunohistochemistry (IHC), immunofluorescence (IF), and in situ proximity ligation assay (iPLA) to survey five common human neoplasms, along with their normal tissue/nonneoplastic counterpart, for the expression of MMP20 and DSPP, using TMA, lysates, and cell lines." (PMID 30932369, 2019).
epithelial neoplasm (1 paper, 2019). A benign or malignant neoplasm that arises from and is composed of epithelial cells. "Our study is based on the hypothesis that DSPP and its cognate MMP20 partner are upregulated in some human epithelial neoplasm where co‐localization and interaction, seen in OSCC, may also take place." (PMID 30932369, 2019). "In summary, we report MMP20 and DSPP expression and interaction in five common human epithelial neoplasms and their normal tissue counterparts: the breast, colon; cervix; prostate; and thyroid." (PMID 30932369, 2019). "Furthermore, we anticipate our data will serve as a major reference and baseline document for studies on the role and significance of MMP20‐DSPP expression in these and other major human epithelial neoplasms." (PMID 30932369, 2019).
MMP20 also shares sentences with these, for which no sentence is quoted: Oral Squamous Cell Carcinomas (3 papers); adenocarcinoma (2); laryngeal squamous cell carcinoma (2); pancreatic cancer (2); age-related macular degeneration (1); benign thyroid neoplasms (1); choroidal neovascularization (1); colonic polyps (1); glioblastoma (1); Graves disease (1); Hypomaturation amelogenesis imperfecta (1); invasive lobular carcinoma (1); leiomyoma (1); mucinous adenocarcinoma (1); mucoepidermoid carcinoma (1); multinodular goiter (1); oral premalignant lesions (1); ovarian serous carcinoma (1); Paget's disease of the breast (1); papillary carcinoma (1); papillary thyroid carcinoma (1); prostate (1); prostate adenocarcinoma (1); prostatic neoplasms (1); subacute thyroiditis (1); thyroid neoplasms (1); transitional cell carcinoma (1).